LOX (lysyl oxidase)
Diseases named in the same sentence as LOX in open-access papers (continued):
Sharing a sentence is not in itself a finding about the gene and the disease.
melanoma (continued). "The mechanical properties of the perisynaptic matrix influence the oscillatory behavior of melanoma cells, as LOX-mediated cross-linking provides stiffness-dependent tuning of frequency and amplitude, and thereby influences whether melanoma cells will migrate or proliferate." (PMID 41463339, 2025). "Additionally, using published H3K27ac ChIP-Seq data, we identified this super-enhancer in the MITF-low metastatic melanoma cell lines (SKmel147, A375, and LOX IMVI) and found loss of H3K27ac in the MITF-high metastatic melanoma cell lines (501MEL, SKmel2, SKmel5, and SKmel239)." (PMID 38319712, 2024). "However, melanoma cells from the SOX10– cell lines (IGR-39 and LOX) formed aggregates whereas the melanoma cells from the SOX10+ cell lines (MM383 and WM278) grew as single-cell suspensions, indicating an added property to mimic the structural character of microtumors." (PMID 36040798, 2022). "Since the involvement of several LOX members in cancer has been extensively characterized, we explored LOXL3 contribution to human cancer by interrogating a comprehensive set of human cancer samples for LOXL3 expression that unveiled an association of LOXL3 to melanoma." (PMID 29229995, 2018). "Both derivatives 10 and 11 elicited 95.25% and 99.73% GI% values against LOX and IMVI, respectively, and cytotoxicity against almost all other cell lines in the melanoma panel." (PMID 41157068, 2025). "Luciferase results demonstrated that MITF silencing reduces the activation levels of miR-579/ZFR promoter as compared to SCR in LOX IMVI and WM266 melanoma cells." (PMID 38472212, 2024). "In our study, we investigated the LOX gene expression in relation to the EMT-related phenotype and differentiation state of melanoma cells for the first time." (PMID 38247872, 2024). "Using immunoprecipitation, we detected an interaction between STAT1 and PARP14 in three melanoma cell lines—MV3, LOX-IMVI, and YUMM2.1." (PMID 37752135, 2023). "In a panel of cultured human malignant melanoma cells (A375V600E, A375NRAS, LOX-IMVI, or G361), it was observed that culture in D2O (90%; 24 h) induces apoptosis." (PMID 33546433, 2021). "Pro-LOX exhibited high expression in HES and lower variable expression in melanoma cells, with WM793 showing the highest expression among them." (PMID 30701028, 2018). "Conversely, we found upregulation of LOX and other LOXL family members, especially LOXL2 and LOXL3, in several human melanoma cell lines." (PMID 30701028, 2018). "Knocking down the expression of LOX and especially LOXL2 in melanoma cells almost completely abrogated the invasive growth capability." (PMID 30701028, 2018). "The cellular and secreted protein levels of LOX and LOXL2 in fibroblasts (HES) and melanoma cells (SK-MEL-147, WM793 and WM239) were then studied." (PMID 30701028, 2018). "First, we studied the mRNA expression levels of LOX and LOXL1-4 in a panel of melanoma cell lines and primary melanoma cells, as well as in primary human melanocytes, fibroblasts, and endothelial cells." (PMID 30701028, 2018). "Regarding melanoma, ALCAM mRNA was markedly elevated in most of the cell lines (LOX, C8161.9, MelJuso) in agreement with the increased expression in primary tumors." (PMID 20929568, 2010). "The transduced melanoma cells MEWO, MV3, and LOX reached IC50 values near the lymphoma and leukemia cell lines with LOX at IC50 = 10.4 nmol/mL (95% CI = 9.3–11.6 nmol/mL), MV3 with IC50 = 189.4 (95% CI = 155.6–230.7 nmol/mL), and MEWO with IC50 = 183.990 (95% CI = 152.1–222.6 nmol/mL)." (PMID 38927982, 2024). "LOX and the LOX family members (LOXL 1-4) are up-regulated in several melanoma cell lines while their down-regulation or inhibition reduces the invasion of melanoma cells." (PMID 38247872, 2024).
melanoma (continued). "Specifically, for melanoma cells, antiproliferative activity potency was maintained for only LOX IMVI cells (GI50 = 1.55 μM), but not for the other cells." (PMID 36834628, 2023). "While the GI50 values of 18a against the LOX IMVI, MALME-3M, and SK-MEL-28 cell lines remained at a similar level to 17a, maintaining GI50 1.59–1.79 μM, the GI50 values were increased by 1.37–9.11-fold against other melanoma cell lines." (PMID 36834628, 2023). "The expression of the lysyl oxidase isoforms LOX and LOXL2 in human A375 melanoma cells were confirmed both at the level of the isolated cells and in the tumour tissue by Western blot analysis, demonstrating the suitability of the corresponding xenograft model." (PMID 37565736, 2023). "Comparing the tumor uptake of the lysine-containing peptide with that of the non-functional analogs indicate the feasibility of lysyl oxidase imaging in melanoma using substrate-based radiotracers." (PMID 29755969, 2018). "Here, we found that inhibition of LOX activity by BAPN had only a minimal, if any, effect on the proliferation of melanoma cells in 2D culture, but markedly inhibited the invasive growth of the cells in 3D Matrigel, particularly when co-cultured with fibroblasts." (PMID 30701028, 2018). "Interestingly, our studies revealed that the depletion of LOX, and particularly that of LOXL2 by shRNAs inhibited both the proliferative capacity and the invasive growth capability of melanoma cells much more effectively than BAPN." (PMID 30701028, 2018). "Our data suggest that inactive pro-LOX functions as a tumor suppressor in ODC- and RAS-transformed mouse fibroblasts by inhibiting cell growth and invasion, and that the mature, active LOX and LOXL2 act as tumor promoters in human melanoma cells by promoting their invasive growth." (PMID 30701028, 2018). "The LOX melanoma cell line showed no protein expression, and therefore was chosen as a control cell line in the subsequent experiments." (PMID 26796342, 2016). "To address whether BAY 87-2243-mediated complex I inhibition is efficient at reducing melanoma tumor growth in vivo, we tested the inhibitor in four BRAF mutant melanoma xenograft models using G-361, SK-MEL-28, A-375, and LOX-IMVI cancer cells." (PMID 26500770, 2015). "LOX is the cell line of choice for study of the functional role of HPA-binding carbohydrates in melanoma metastasis, as it shows intense HPA binding, does not express CEACAM1 and shows only low L1 expression." (PMID 17262079, 2007). "The high HPA reacting LOX melanoma line shows extensive pulmonary metastatic formation with no extrapulmonary colonies, whereas the low HPA reacting FEMX-I cells give only extrapulmonary metastases with no detectable colonies in the lungs." (PMID 8198963, 1994). "As for 15a, overall antiproliferative activity was relatively decreased compared to 14a–c; in particular, although the inhibition ability against B-RAFV600E of 15a was slightly greater, it did not inhibit the growth of melanoma cells, except LOX IMVI and UACC-62 in a better fashion." (PMID 36834628, 2023). "Thus, our studies reveal that inactive pro-LOX (together with Lox propeptide) functions as a tumor suppressor in ODC- and RAS-transformed murine fibroblasts by inhibiting cell growth and invasion, and active LOX and LOXL2 as tumor promoters in human melanoma cells by promoting their invasive growth." (PMID 30701028, 2018). "Altogether, therapeutic targeting of the LOX family members, especially LOX and LOXL2, by promoting the tumor suppressive function of LOX and/or inhibiting the activity or expression of these enzymes, may offer viable ways to combat melanoma and other cancers." (PMID 30701028, 2018). "As chemokine decoy receptors (D6, DARC, CCX-CKR) were expressed in glioma as well as LOX cells, they could be ruled out as mediators for tm-chemokine effects that were absent in the melanoma cells." (PMID 26796342, 2016).
melanoma (continued). "In addition to cell lines, we also compared the mRNA expression levels of LOX and LOXL1-4 in clinical tissue specimens of human benign nevi and malignant melanomas, and found LOXL1 (fold 1.6; p = 0.0028) and LOXL2 (fold 2.0; p = 0.00016) to be significantly upregulated in the primary melanomas." (PMID 30701028, 2018). "LOX melanoma cells do not endogenously express CXCL16, nor CXCR6, and so, we generated LOX clones expressing transmembrane CXCL16 (LOX-CXCL16) or a C–terminally truncated version of transmembrane CXCL16 (LOX-ΔCXCL16) and a clone from the empty expression vector (LOX-pcDNA)." (PMID 28698473, 2017).
gastric cancer (51 papers, 2007 to 2025). A primary or metastatic malignant neoplasm involving the stomach. "For example, the expression levels of LOX are closely related to gastric cancer patient prognosis, with low expression usually associated with poorer clinical outcomes." (PMID 40661776, 2025). "Studies have demonstrated that LOX facilitated the interaction of tumor cells with tumor-associated fibroblasts, promoting the invasion of gastric cancer and liver metastases." (PMID 39251966, 2024). "Firstly, the HIF1A-AS2/RP11-366L20.2-miRNA-29c axis was identified as one of the causes of high expression of LOX in gastric cancer, which needs to be verified by further molecular experiments." (PMID 35047494, 2021). "In summary, we suggest that the differential expression of the HIF1A-AS2/RP11-366L20.2-miRNA-29c axis is considered as one of the causes of high expression of LOX in gastric carcinoma." (PMID 35047494, 2021). "LOX is highly expressed in gastric cancer cells with high invasiveness and is intimately associated with distal metastases in gastric cancer." (PMID 31777578, 2019). "In another study, LOX was found to be inactivated by methylation and loss of heterozygosity in human gastric cancers." (PMID 28036074, 2016). "Increased LOX expression has been associated with a worse outcome in patients with astrocytomas, non-small lung cancer and gastric cancer." (PMID 26501565, 2015). "LOX is highly expressed in invasive tumors, such as uveal melanoma, colorectal cancer, and gastric cancer, and it is closely associated with metastasis and poor patient outcomes." (PMID 25060181, 2014). "Additionally, in gastric cancer, lysyl oxidase (LOX) secreted by cancer-associated fibroblasts (CAFs) activates the TGFβ/IGF1 signaling pathway, augmenting glycolysis and resulting in lactate accumulation." (PMID 40057816, 2025). "We speculated whether the overexpression of LOX caused an alteration of the tumor microenvironment in gastric cancer." (PMID 35047494, 2021). "In addition, LOX (lysyl oxidase), a cell-associated enzyme that functions in extracellular matrix biology has been identified as a tumor suppressor gene in gastric cancer." (PMID 18828910, 2008). "The association between the expression of Lysyl oxidase (LOX) and its clinicopathological parameters and prognosis in patients with gastric cancer (GC) is still disputed." (PMID 36202905, 2022). "LOX overexpression by CAFs correlates with increased tumor cell proliferation, migration, and invasion in gastric cancer tissues." (PMID 40906383, 2025). "Studies have reported that the LOX protein is highly expressed in gastric cancer tissues, and its expression has been correlated with poor overall survival." (PMID 40906383, 2025). "It identifies that cancer-associated fibroblasts (CAF) secrete lysyl oxidase (LOX), which activates the TGFβ signaling pathway and increases insulin-like growth factor 1 (IGF1) levels in gastric cancer cells." (PMID 39897050, 2025). "Beyond collagen synthesis, CAFs in gastric cancer are key producers of matrix-modifying enzymes—including LOX and MMPs—that drive ECM cross-linking and focal degradation." (PMID 40906383, 2025). "Studies indicate that the expression of both MMP-9 and MMP-2 correlates with the expression of LOX in gastric cancer biopsies." (PMID 40906383, 2025). "A study shows that LOX overexpression is significantly correlated with T-stage progression in gastric cancer." (PMID 40906383, 2025). "LOX is highly expressed in gastric cancer tissues, and its expression is significantly and positively correlated with the stage of gastric cancer, thus affecting the overall survival of patients 16-17." (PMID 38434983, 2024). "The relative expression of PDGFRα and PDGFRβ in gastric cancer cells was up-regulated with increasing LOX and downregulated with increasing BAPN (P < 0.05)." (PMID 38434983, 2024). "The number of VM structures in gastric cancer cells gradually increased with increasing LOX concentrations." (PMID 38434983, 2024).
gastric cancer (continued). "The results found that the concentration of LOX was positively correlated with the VM number of gastric cancer cells." (PMID 38434983, 2024). "Then, AG1295 (10 μM) or AG1296 (5 μM) concentrations were added to inhibit PDGFR function, and different concentrations of LOX or BAPN were added to detect VM formation in gastric cancer cells." (PMID 38434983, 2024). "With inhibition of PDGFRα and PDGFRβ using AG1295 or AG1296, VM formation in gastric cancer cells decreased (P <0.05), but the number of VM structures increased while LOX was added (P < 0.05)." (PMID 38434983, 2024). "The relative expression of PDGFR-α and PDGFR-β in gastric cancer cells was augmented with the increase in LOX concentration." (PMID 38434983, 2024). "Meanwhile, LOX+fibroblasts interact with M2 Macrophage to promote gastric cancer progression and metastasis, forming a specific immunosuppressive microenvironment." (PMID 39251966, 2024). "In this study, gastric cancer tissues and cells were used to investigate the role of LOX in the formation of VM." (PMID 38434983, 2024). "This study explored LOX expression and the number of VM structures in clinical specimens of 49 patients with gastric cancer." (PMID 38434983, 2024). "This study investigated the effect of LOX on VM formation in gastric cancer cells and its potential mechanism." (PMID 38434983, 2024). "The relative expression of PDGFRα and PDGFRβ in gastric cancer cells increased with increasing LOX concentration but decreased with increasing BAPN concentration." (PMID 38434983, 2024). "The formation of VM was measured by double staining with CD34 and Periodic acid-Schiff (PAS) in gastric cancer tissue slices, and the correlation between LOX and VM was analyzed with Pearson's correlation analysis." (PMID 38434983, 2024). "Gastric cancer cell line BGC-803 was treated with LOX, β-aminopropionitrile (BAPN, an inhibitor of LOX), and AG1295 or AG1296 (inhibitors of the platelet-derived growth factor receptor)." (PMID 38434983, 2024). "In gastric cancer, the downregulation of LOX expression can downregulate the expression of MMP-2 and MMP-9 in cancer cells." (PMID 39132501, 2024). "The relative expression of LOX in gastric cancer samples from the T3-T4 group was higher than in the T1-T2 group (0.33 ± 0.12 vs. 0.22 ± 0.07), P < 0.05." (PMID 38434983, 2024). "To confirm this finding, we added exogenous LOX or LOX inhibitor (BAPN) to the gastric cancer cell line BGC-803 and observed VM formation during cell culture." (PMID 38434983, 2024). "Literature shows that the expression level of LOX in gastric cancer is usually high, which is consistent with the results of TCGA and GEO databases." (PMID 39132501, 2024). "The relative expression of PDGFR was positively correlated with LOX in gastric cancer tissue, rLOX/PGGFR=0.634, P < 0.0001." (PMID 38434983, 2024). "We demonstrated that LOX can promote the formation of VM in gastric cancer and then promote the growth, invasion, and metastasis of gastric cancer." (PMID 38434983, 2024). "PDGFR levels in the T3+T4 and metastasis groups were relatively higher (P <0.01) and positively correlated with LOX levels in gastric cancer specimens (P < 0.01)." (PMID 38434983, 2024). "To evaluate LOX's effect on gastric cancer cell VM formation, we treated cells with different concentrations of LOX or BAPN." (PMID 38434983, 2024). "In gastric cancer cells, LOX concentration was positively correlated with the degree of VM, and BAPN concentration was negatively correlated with the degree of VM (P <0.05)." (PMID 38434983, 2024). "LOX concentrations were positively correlated with the number of VM formations in human gastric cancer cells (rAG1295/VM = 0.878, rAG1296/VM = 0.935, P < 0.05)." (PMID 38434983, 2024). "RGS2, GJA1, GPX3, and LOX were less expressed in gastric cancer tissues than in paracancerous tissues (P<0.05)." (PMID 39132501, 2024).